TRAV24 (T cell receptor alpha variable 24)
Description:
V region of the variable domain of T cell receptor (TR) alpha chain that participates in the antigen recognition. Alpha-beta T cell receptors are antigen specific receptors which are essential to the immune response and are present on the cell surface of T lymphocytes. Recognize peptide-major histocompatibility (MH) (pMH) complexes that are displayed by antigen presenting cells (APC), a prerequisite for efficient T cell adaptive immunity against pathogens. Binding of alpha-beta TR to pMH complex initiates TR-CD3 clustering on the cell surface and intracellular activation of LCK that phosphorylates the ITAM motifs of CD3G, CD3D, CD3E and CD247 enabling the recruitment of ZAP70. In turn ZAP70 phosphorylates LAT, which recruits numerous signaling molecules to form the LAT signalosome. The LAT signalosome propagates signal branching to three major signaling pathways, the calcium, the mitogen-activated protein kinase (MAPK) kinase and the nuclear factor NF-kappa-B (NF-kB) pathways, leading to the mobilization of transcription factors that are critical for gene expression and essential for T cell growth and differentiation. The T cell repertoire is generated in the thymus, by V-(D)-J rearrangement. This repertoire is then shaped by intrathymic selection events to generate a peripheral T cell pool of self-MH restricted, non-autoaggressive T cells. Post-thymic interaction of alpha-beta TR with the pMH complexes shapes TR structural and functional avidity.
Synonyms: TCRAV18S1; TCRAV24S1
Gene: T-cell receptor variable (V) gene on chromosome 14 (22,105,343 to 22,105,846, forward strand). Ensembl gene ENSG00000211805.
Subcellular location: Cell membrane
Gene Ontology:
Biological process: response to bacterium
Cellular component: plasma membrane
Homologues: Orthologues: rabbit TRAV24 (73% identical), dog TRAV24 (69% identical). Paralogues in human: TRAV36DV7 (46% identical), TRAV21 (44% identical), TRAV20 (43% identical), TRAV39 (41% identical), TRAV7 (41% identical), TRAV13-1 (39% identical), TRAV10 (38% identical), TRAV34 (36% identical), TRAV6 (36% identical), TRAV5 (35% identical), TRAV17 (34% identical), TRAV27 (33% identical), and 11 more.
Diseases named in the same sentence as TRAV24 in open-access papers:
TRAV24 is named in the same sentence as 2 diseases in open-access papers, as found by Europe PMC text mining. Sharing a sentence is not in itself a finding about the gene and the disease.
TRAV24 shares sentences with these, for which no sentence is quoted: glioma (1 paper); tumor (1).